IL2 (interleukin 2)
Diseases named in the same sentence as IL2 in open-access papers (continued):
Sharing a sentence is not in itself a finding about the gene and the disease.
cancer (continued). "IL‐2 or IL‐15 can significantly enhance the proliferation of CAR‐T cells in tumors thereby prolonging their survival and anti‐cancer function in vivo." (PMID 40395752, 2025). "Interleukin-2 (IL-2) is a cytokine vital for CD8+ T cell activation and proliferation, holding great potential for cancer immunotherapy." (PMID 40009662, 2025). "In the TME, Th1, and Th9 subsets of CD4+T-cells enhance CD8+T-cell antitumor activity through cytokines like IL-2, IFN-γ, and IL-9, correlating with improved outcomes across cancers." (PMID 40260236, 2025). "The birinapant treatment significantly promoted the migration of IL2- and anti-CD3-activated Jurkat T cells from the upper chamber to the cancer cell culture in the bottom chamber." (PMID 40057483, 2025). "The interaction between CD25–IL-2 is critical for the beneficial synergistic effect of the PD-1-specific ICI and IL-2 combination, which has shown considerable activity in cancer patients." (PMID 41009359, 2025). "Cytokines have a substantial track record as anti-cancer treatments, starting from the 1970s, when interferon (IFN)-α and IL-2 were the first cytokines utilized in cancer therapy." (PMID 39852848, 2025). "Specifically, we engineer TGF-β-gated IL-2 (TGF-β→IL-2) and IL-10-gated IL-2 (IL-10→IL-2) cytokine adaptors that reverse T cell inhibition and have potential applications in cancer therapy." (PMID 40069219, 2025). "Radiolabeled IL-2 (e.g., 18F-IL-2) has been used in PET imaging to monitor the activation state and distribution of immune cells, playing a vital role in evaluating cancer patients’ immune responses and optimizing immunotherapy strategies." (PMID 39911388, 2025). "Historically, cytokines have been utilized as anti-cancer drugs for more than fifty years, with IFN-α and IL-2 being the first to be employed." (PMID 40362536, 2025). "In this secondary analysis of our randomized controlled CRBP-TS trial, we evaluated the effects of HOET on the cytokines IL-1ß, IL-2, IL-6, IL-10, IL-12p70, TNF-α, IFN-γ, and the mGPS of 145 cancer patients." (PMID 40498221, 2025). "MPE T cells also readily expanded in the presence of high-dose IL-2 and demonstrated MHC class I-dependent killing of autologous cancer cells." (PMID 41415427, 2025). "Compared to IL‐2 or IL‐15, CAR‐T cells that secrete IL‐23 not only demonstrate superior anti‐cancer functionality but also offer unique safety advantages due to the specific mechanism of IL‐23 production." (PMID 40395752, 2025). "Upon co-incubation with AXL-positive cancer cells, the mfhAXL CAR-T cells were specifically activated to secrete IL-2 and IFN-γ, indicating their selective responsiveness to the antigen." (PMID 40299452, 2025). "Interleukin-2 (IL-2) and Interferon-γ (IFN-γ) are crucial for bolstering immune responses against cancer cells, with therapeutic applications in certain malignancies." (PMID 39980555, 2025). "Historically, cytokines such as IL-2 and IFN-α were the first immunotherapies approved for cancer treatment." (PMID 40508202, 2025). "The combination therapy of a stimulator of interferon gene (STING) agonist with extended half-life IL-2 and anti-PD-1 (CIP therapy) considerably enhances the cancer response in TNBC models by upregulating the expression of IFNAR-1 and CD25 on lung NK cells." (PMID 40303301, 2025). "TGFβ1 controls the activities of inflammatory genes like IL-2 and TNF-α, which is a specific way that it links inflammation to cancer." (PMID 39811247, 2025). "We explored the relative merits of employing CD25-biased versus CD25-blocking anti-IL-2 antibodies, revealing the unexpected therapeutic advantage for CD25-biased anti-IL-2 antibodies in the context of ICI combination therapy for cancer treatment." (PMID 40789741, 2025). "Comparisons with IL-2, IL-2 + anti-CD16 mAbs, IL-2 + anti-CD16 mAbs + sAJ2, IL-12, IL-15, IL-18, OSCSCs, and K562-expanded NK cells demonstrate the remarkable anti-cancer functions of sNK cells." (PMID 40805135, 2025).
cancer (continued). "We have previously constructed an oncolytic adenovirus coding for human TNFα and IL-2, Ad5/3-E2F-d24-hTNFα-IRES-hIL2 (TILT-123 or igrelimogene litadenorepvec) allowing selective replication in cancer cells and high local expression of these transgenes." (PMID 40211048, 2025). "The secretion of IL-2, IL-5, IL-8, MCP-1, and VEGFA was significantly reduced in both the sh-MMP28-1 and sh-MMP28-2 AsPC-1 and BxPC-3 cancer cell lines." (PMID 39972459, 2025). "PD-L1 on cancer cells binds to PD-1 on antigen-stimulated T cells, triggering T-cell exhaustion and reducing IFN-γ and IL-2 secretion." (PMID 40977688, 2025). "In carcinoma patients, CRT-NP treatment enhanced MCP-1 serum levels whereas in STS patients GM-CSF, IL-2, IL-6 & IL-18 were enhanced." (PMID 40386779, 2025). "In line with this, gene therapy techniques that involve the use of adenoviruses as transfer vectors expressing TNF-α, IL-2, IL-12, IFN-a2b, IFN-β, or GM-CSF have been used to modulate cytokine expression in several cancer indications." (PMID 38256080, 2024). "Several cytokines, including leptin, IL-1B, IL-6, IL-8, IL-23, IL-17, and IL-10, stimulate cancer progression, while others, including IL-2, IL-12, and IFN-γ, inhibit cancer proliferation and/or invasion." (PMID 37979099, 2024). "In particular, IL-2, TNF-α, and IL-6 play crucial roles in the immune response to inflammation as well as cancer." (PMID 39317690, 2024). "High doses of IL-2 can invigorate NK cells and CD4+ and CD8+ T cells, and IL-2 was one of the earliest cancer immunotherapies to be approved by the Food and Drug Administration (FDA)." (PMID 39339165, 2024). "Processes related to inflammation, such as IL-2/STAT5, TNF-alpha signaling via NF-κB and inflammatory response were significantly higher in NrasG12D/PtenKO cancer cells and bulk tumors compared to their NrasG12V-driven counterparts." (PMID 38519484, 2024). "IL-2 leads to the activation of the JAK1, JAK3, STAT1, STAT3, STAT5A, STAT5B, and PI3K/AKT pathways, which affect the progression of cancer." (PMID 39272802, 2024). "Proinflammatory cytokines such as interleukin-2 and IFN-α trigger potent host innate immune responses, which, in turn, induce cross-priming and recruitment of T-cells to invoke an anti-cancer effect." (PMID 38256021, 2024). "Some studies and publications have reported a relationship between dysregulation of expression of some cytokines, including IL-1, IL-2, IL-4, IL-6, LPC2, TNF-α, etc., and incidence of cancer, cancer invasivity, and metastases." (PMID 38541074, 2024). "Interleukin-2 (IL-2) and interferon-alpha (IFN-α) are among the first cytokines approved for cancer treatment." (PMID 39767566, 2024). "CD244 is increasingly expressed on exhausted CD8+ T cells with decreased production of IL-2 and IFN-γ in both mouse and human cancers." (PMID 38633624, 2024). "Immunotherapy using inflammatory cytokines, such as interleukin (IL)-2 and interferon (IFN)-α, has been clinically validated in treating various cancers." (PMID 39290693, 2024). "IL-2 therapy, which enhances the function of CD8 + T cells, was initially employed as the cornerstone of immunotherapy against cancer." (PMID 39218982, 2024). "MDNA11 is a long-acting “beta-only” recombinant interleukin-2 (IL-2) superkine engineered to activate immune effector cells, such as CD8+ T cells and NK cells, which target cancer cells while minimizing the activation of immunosuppressive regulatory T cells." (PMID 39685500, 2024). "TG4010 is a cancer vaccine expressing human MUC1 and IL-2 genes (MVA-MUC1-IL-2) composed of a highly attenuated modified Ankara virus strain." (PMID 39491020, 2024).
cancer (continued). "This control serves to suppress the IL-2/STAT5 pathway, offering insights into the functional interplay between TGF-β and Bcl6 in cancer immunity, as well as providing potential targets for cancer immunotherapy." (PMID 38780677, 2024). "IL2, a 15.5 kDa glycoprotein, is mainly secreted by antigen stimulated CD4 + T cell which play a key role in the cancer immunotherapy." (PMID 38554155, 2024). "In another set of studies, an IL-2/CD25 fusion protein with selectivity towards the high-affinity IL-2R was shown to better amplify cancer-vaccine activated CD4+ and CD8+ T cell responses compared to WT IL-2 treatment." (PMID 39114660, 2024). "We demonstrate that toxicity can be decoupled from antitumor activity in preclinical models by limiting IL2 signaling to CD8+ T cells, supporting the development of CD8+ T cell–selective IL2 for the treatment of cancer." (PMID 38563906, 2024). "Our study results suggest a robust association between the P3H score and various cancerous pathways in pan-cancer, including IL6-JAK-STAT3 signaling, IL2 STAT5 SIGNALING response, and the inflammatory response." (PMID 38706607, 2024). "Among dozens of cytokine payloads, IL2, IL12, and TNF have emerged as some of the most efficient immunomodulatory proteins in preclinical models of cancer." (PMID 38448543, 2024). "Many cytokines, including GM-CSF, IL-7, IL-12, IL-15, IL-18, and IL-21, have entered clinical trials for people with advanced cancer, while the FDA has approved interferon-alpha and IL-2." (PMID 38360737, 2024). "Preclinical studies of the T-cell growth factor activity of IL2 resulted in this CK becoming the first immunotherapy approved ~30 years ago by the US Food and Drug Administration (FDA) to treat cancer." (PMID 38789577, 2024). "IL-2 was modified by the addition of glycosylphosphatidylinositol (GPI) domain and delivered to the cancer cells by the vaccinia virus." (PMID 37046608, 2023). "The relationship between IL2 and IL15 has been demonstrated, including cancer therapy, as well as the relationship between IL2 and IL17A, and between IL15 and IL17A." (PMID 37691946, 2023). "Enhanced host immune responses (a significant increase in IL-2, IL-6, IFN-γ,CD56+ cells and NK activity compared with baseline) in patients with advanced-stage cancer." (PMID 36969071, 2023). "To date, IL-2 and interferon-α (IFN-α) are the only two cytokine drugs for the treatment of cancers approved by the U.S. Food and Drug Administration (FDA)." (PMID 36936961, 2023). "Although both HM2 and D4 CAR T cells exhibited similar killing ability, D4 CAR T cells triggered 2- to 7-fold more secretion of cytokines including IFN-γ, IL-2, and TNF-α than HM2 CAR T cells after exposure to GPC1-positive cancer cells." (PMID 37031249, 2023). "Furthermore, exploring combination therapies—IL-2/IL-2R-targeted therapies coupled with traditional cancer treatments like chemotherapy, radiotherapy, or other immunotherapies like checkpoint inhibitors—could optimize cancer treatment efficacy." (PMID 37516849, 2023). "TRM cells release vital effector molecules and cytokines like IL-2, IFN-γ, TNF-α, and GzmB, enabling rapid responses against cancer cells." (PMID 37892995, 2023). "In other words, a combination of CU06-1004 and IL-2 drugs is a new promising strategy to reduce severe VLS and maintained the immune response to cancer for a long time." (PMID 37711172, 2023). "Studies have shown that chemokines and cytokines, such as TNF-α, IL-2, and chemokine CCL2, play a role in the formation of the cancer microenvironment and are responsible for the migration of inflammatory cells and cancer cells." (PMID 37968670, 2023). "MTE increased secretion of DDPIV, IL-2 and IFN-γ, promoting the immune response of TILs to cancer cells." (PMID 37649480, 2023).
cancer (continued). "Th1 CD4+ T cells secrete cytokines such as IL2 and IFNγ, which promote effector T cell proliferation and induce MHC expression on the surface of cancer cells, respectively." (PMID 37830618, 2023). "Our own studies confirm the influence of cytokines (i.e., concentrations of IL-1A, IL-1B, IL-2, IL-6, IL-10, TNF, and IL-4) on the emergence of fatigue in all its dimensions in patients with cancers of the reproductive organs at various stages of treatment." (PMID 36834426, 2023). "The clinical approval of recombinant interleukin-2 (IL-2) and interferon-α (IFN-α) cytokines for treating several malignant diseases marked a milestone in cancer immunotherapy, even if based on rather limited efficacy." (PMID 37637207, 2023). "The clinical application of both HD IL-2 therapy, as well as use in combination with ex vivo generated LAK or CIK cells, has demonstrated antitumor effects for several cancers, albeit with significant toxicities." (PMID 37737264, 2023). "IL-2 seems to be a potential AKNA-controlled factor whose implications in helper T-cell activation and cancer are relevant for the appropriate function of cells." (PMID 36835622, 2023). "Dual-RevCAR T-cells secreted increased amounts of GM-CSF, IFN-γ, IL-2 and TNF-α only upon engaging CEA+ EpCAM+ cancer cells upon simultaneous presence of anti-CEA and anti-EpCAM RevTMs." (PMID 38169746, 2023). "Another study has investigated enhancing the immune response against cancer treatment, in which TMC-based NPs were synthesized and fabricated with DOX and interleukin-2 (rhIL-2)." (PMID 38202616, 2023). "HITT overexpression by cancer cells elevated cytotoxic T lymphocyte (CTL) activity, as indicated by increased secretion of IL-2 and IFN-γ in the culture medium." (PMID 37014700, 2023). "To date, IL-2 is the only cytokine, besides INF, approved by the FDA in single-agent cancer therapy." (PMID 37046608, 2023). "The results of this study show that The active components of the A. cantoniensis Hance can affect cancer signaling pathway, endocrine resistance, PI3K-AKt signaling pathway, MAPK signaling pathway, IL-2/IL-6/IL-17 signaling pathway and TNF signaling pathway." (PMID 37035802, 2023). "To characterize the polyfunctionality of cellular immune response, we also quantified IL-2 and TNF-α as T-cell-specific cytokines in a cohort of 50 HCWs and in all cancer patients." (PMID 37376576, 2023). "We demonstrate the suppression of high-dose IL-2-induced side effects and the improvement of anti-cancer effects through combined CU06-1004 and IL-2." (PMID 37711172, 2023). "By addressing these questions, we aim to provide a comprehensive overview of IL-2 and IL-2R’s functions in the TME, catalyzing further research toward developing more effective cancer immunotherapies." (PMID 37516849, 2023). "Additional examples of dual-cytokine fusions described in the literature and tested in preclinical cancer models include those based on anti-CD30 + IL2/IL12, anti-CD38 + IL2/TRAIL, and anti-HER2 + IL12/IL2 or GM-CSF." (PMID 37092450, 2023). "CRISPR/Cas–mediated HITT KO produced opposing results regarding both IL-2 and IFN-γ secretion and T cell–mediated cancer-killing effects." (PMID 37014700, 2023). "With the emergence of cytokine therapy for cancer, the four cytokines of the common cytokine receptor γ chain (γc, CD132) family, containing interleukin-2 (IL-2), IL-7, IL-15, and IL-21 are dictated to regulate the T cell stemness formation and maintenance." (PMID 38049832, 2023). "Some pathways showed dual roles such as Kras signaling, interferon gram and alpha response, IL6/JAK/STAT3, IL2/STAT5 signaling were negatively enriched in HOXC10 for CESC, COAD, ESCA, HNSC but were positively enriched in HOXC10 for other cancers." (PMID 38154103, 2023).
cancer (continued). "This supports that treatment with Salmonella + Alb-IL2 drives the proliferation of CD4 and CD8 T cell populations which likely contributes to the observed anti-cancer effects." (PMID 35962391, 2022). "Ads that were engineered to express immune-stimulatory cytokines and other immune-modulatory molecules such as TNF-α, IL-2, BiTE, CD40L, 4-1BBL, GM-CSF, and IFN have shown promising outcome in treatment of cancer." (PMID 35756634, 2022). "These receptors are highly expressed by cancer cells and upon interaction with CTLA-4 results in reduction in T cell proliferation and interleukine-2 (IL-2) production." (PMID 36551637, 2022). "Although several publications have indicated an association between fatigue and systemic cytokines such as IL-1β, IL-2, IL-6, IP-10, and TNF in cancer patients, the results are conflicting." (PMID 36350483, 2022). "Many studies demonstrate that Th1 cells have a key role in combating cancers by secreting IFN-γ, IL-2, and TNF-α." (PMID 35433680, 2022). "To consider the effect of IL-2 therapy on the GVL activity, we conducted HSCT for the recipients bearing cancer cells." (PMID 35983059, 2022). "Furthermore, preventive administration of L. casei BL23 suppressed cancer occurrence in vivo through systemic recruitment of NK cells, while therapeutic administration remarkably inhibited cancer cell growth through upregulation of IL-2 and activation of T cells." (PMID 36726985, 2022). "αROR1-CAR T cells can be activated by ROR1-ScFv conjugation, releasing cytokines including IL-2, IFN-γ, and TNF-α and inducing cytotoxicity in cancer cells." (PMID 35484298, 2022). "One of these mechanisms activates the immune system by inducing cytokine secretion (IL-2 and IFN-gamma) and attracts CD56 natural killer and CD8 cytotoxic lymphocytes into infected cancer tissue." (PMID 35936786, 2022). "Among them, more attention has been spent on the ICIs, anti-tumor cytokines (IL-2 and IFN-ɑ), cancer cell vaccine, and adoptive cell transfer (ACT)." (PMID 36510217, 2022). "In contrast, cancer patients demonstrated a significant reduction in IFN‐γ (p < 0·0001) and IL‐2 (p = 0·026) SARS‐CoV‐2‐specific T‐cell responses at 3 months post‐vaccination, with several patients notable for sudden, large decreases in T‐cell responses." (PMID 34775604, 2022). "Utilizing these characteristics, IL-21 performed much better than IL-2 or IL-15 during in vitro generation of antigen-specific CD8+ CTL and in an in vivo murine model of cancer immunotherapy." (PMID 35432319, 2022). "Immune checkpoint inhibitors, cytokines like interleukin 2 (IL-2) and interferon-alpha (IFN), and the cancer vaccine sipuleucel-T have all been licensed and approved by the FDA for the treatment of various cancers." (PMID 35744922, 2022). "CD4+ Th1 cells secrete IL-2 and IFN to activate and promote the proliferation of CD8+ T cells, which subsequently release cytotoxic cytokines and kill cancer cells directly." (PMID 35061208, 2022). "The most studied cytokines in cancer therapy are granulocyte-macrophage colony-stimulating factor (GM-CSF), vascular endothelial growth factor (VEGF), interluekin-2 (IL-2), granulocyte colony-stimulating factor (G-CSF), and interferon gamma (IFN-γ)." (PMID 36297474, 2022). "For example, interferon γ response, interferon α response, IL2 STAT5 signalling, inflammatory response, and allograft rejection were enriched in each cancer, which indicated that cuproptosis and necroptosis were positively related to these oncogenic pathways." (PMID 36186436, 2022).